NCCRP1 (NCCRP1, F-box associated domain containing)
Description:
Promotes cell proliferation.
Synonyms: NCCRP-1; FBXO50; LOC342897
Tractability: No criterion of Open Targets' tractability assessment is met for any kind of drug.
Gene: Protein-coding gene on chromosome 19 (39,196,964 to 39,201,884, forward strand). Ensembl gene ENSG00000188505.
Subcellular location: Cytoplasm
Subcellular location (Human Protein Atlas): Cytosol
Gene Ontology:
Molecular function: protein binding; ubiquitin protein ligase activity
Biological process: positive regulation of cell population proliferation; ERAD pathway; glycoprotein catabolic process; SCF-dependent proteasomal ubiquitin-dependent protein catabolic process
Cellular component: cytoplasm; cytosol; extracellular exosome; SCF ubiquitin ligase complex
Genetic constraint (gnomAD): Loss-of-function variants: 32 observed, 30.79 expected, observed/expected ratio (o/e) 1.04, 90% interval 0.78 to 1.4. The upper end of that interval is the gene's LOEUF score, 1.4, which puts it in group 5 of 6, group 1 being the genes least tolerant of losing a copy. Missense variants: 372 observed, 348.2 expected, observed/expected ratio (o/e) 1.07, 90% interval 0.98 to 1.16. Synonymous variants: 172 observed, 154.89 expected, observed/expected ratio (o/e) 1.11, 90% interval 0.98 to 1.26.
Homologues: Orthologues: chimpanzee NCCRP1 (99% identical), macaque NCCRP1 (97% identical), pig NCCRP1 (83% identical), dog NCCRP1 (81% identical), rabbit NCCRP1 (80% identical), rat Nccrp1 (75% identical), mouse Nccrp1 (74% identical), guinea pig NCCRP1 (73% identical), tropical clawed frog nccrp1 (43% identical), zebrafish nccrp1 (33% identical). Paralogues in human: FBXO27 (29% identical), FBXO2 (28% identical), FBXO17 (26% identical), FBXO6 (25% identical), FBXO44 (24% identical).
Diseases named in the same sentence as NCCRP1 in open-access papers:
NCCRP1 is named in the same sentence as 14 diseases in open-access papers, as found by Europe PMC text mining. Sharing a sentence is not in itself a finding about the gene and the disease. The quoted sentences say what the papers report.
pancreatic cancer (3 papers, 2011 to 2021). "And high expression of NCCRP1 in patients with pancreatic cancer was associated with a poor prognosis." (PMID 34956313, 2021). "But we found that even though some genes (RNF7, NPEPPS, and NCCRP1) were down-regulated in tumor group, patients with pancreatic cancer with high expression of these genes had a worse prognosis." (PMID 33414811, 2020). "NCCRP1 showed the highest expression in the Su.86.86, Hup-T4 and Hs700T pancreatic cancer cell lines and the MDA-MB-415, SK-BR-3 and BT-474 breast cancer cell lines." (PMID 22087255, 2011). "Using multivariate Cox regression analysis, we detected eight optimal ubiquitination-related genes (RNF7, NPEPPS, NCCRP1, BRCA1, TRIM37, RNF25, CDC27, and UBE2H) and then used them to construct a risk model to predict the prognosis of pancreatic cancer patients." (PMID 33414811, 2020). "The expression of NCCRP1 and CA9 was measured by QRT-PCR in 16 pancreatic cancer cell lines and 21 breast cancer cell lines." (PMID 22087255, 2011). "Furthermore, in a panel of 16 pancreatic cancer cell lines and 21 breast cancer cell lines, NCCRP1 and CA9 expression were inversely correlated in certain cell lines; NCCRP1 was weakly expressed or absent when CA9 mRNA was highly expressed, and vice versa." (PMID 22087255, 2011).
esophageal squamous cell carcinoma (2 papers, 2021 to 2023). Esophageal squamous cell carcinoma (ESCC) is a type of esophageal carcinoma (EC) that can affect any part of the esophagus, but is usually located in the upper or middle third. "Inversely, another study found that esophageal squamous cell carcinoma patients with lower NCCRP1 expression tended to have an increased risk of disease recurrence and dismal survival prognosis versus those with higher NCCRP1 expression, suggesting a putative tumour-suppressive role of NCCRP1." (PMID 38106991, 2023).
gastric cancer (1 paper, 2023). A primary or metastatic malignant neoplasm involving the stomach. "In gastric cancer, higher NCCRP1 expression is associated with shorter recurrence-free and overall survival time, as it promotes proliferation, movement, and incursion of gastric cancers." (PMID 38106991, 2023).
metastatic melanoma (1 paper, 2020). A melanoma that has spread from its primary site to another anatomic site. "For the genes related to adverse prognosis, NCCRP1 was also identified as an independent risk prognostic predictor for metastatic melanoma." (PMID 33392203, 2020).
Miscarriage (1 paper, 2023). A pregnancy that ends at a stage in which the fetus is incapable of surviving on its own, defined as the spontaneous loss of a fetus before the 22th week of pregnancy. "Interestingly, NCCRP1 plays a role in the positive regulation of cell proliferation and displays differential expression in individuals who experienced multiple miscarriages." (PMID 37834424, 2023).
psoriasis (1 paper, 2015). An autoimmune condition characterized by red, well-delineated plaques with silvery scales that are usually on the extensor surfaces and scalp. "However, given distinct functional properties of psoriasis-specific and non-specific DEGPs, it may be appropriate for such applications to assign greater emphasis to the most psoriasis-specific DEGPs, such as NCCRP1, DBI and GLTP." (PMID 26251673, 2015).
squamous cell carcinoma of the skin (1 paper, 2011). "The cancer-derived tissues with high NCCRP1 expression included the squamous cell carcinoma of the skin and cancers of the female reproductive organs." (PMID 22087255, 2011).
triple-negative breast carcinoma (1 paper, 2023). An invasive breast carcinoma which is negative for expression of estrogen receptor (ER), progesterone receptor (PR), and human epidermal growth factor receptor 2 (HER2). "A most recent study suggested that NCCRP1 was highly expressed in triple-negative breast cancers (TNBCs) and its overexpression could markedly enhance cell proliferation." (PMID 38106991, 2023).
tumor (6 papers, 2017 to 2024). "NCCRP-1 plays a crucial role in the immune system by lysing tumor target cells, protozoan parasites, and virus-infected cells." (PMID 36539822, 2022). "Among the eight genes, five genes (BRCA1, TRIM37, RNF25, CDC27, and UBE2H) were significantly upregulated and three genes (RNF7, NPEPPS, and NCCRP1) were significantly down regulated in the tumor tissues." (PMID 33414811, 2020). "Evidence shows that NCCRP1 plays an essential role in tumour development, and whether it acts as a tumour suppressor gene or oncogene depend upon tumour types." (PMID 38106991, 2023). "There are few studies on the role of NCCRP1, RNF25, and UBE2H in cancer, but the existing research results suggest that these three genes also have the potential to become new tumor biomarkers or targets for cancer." (PMID 33414811, 2020). "Of the eight genes we identified, three genes (RNF7, NPEPPS, and NCCRP1) were down-regulated and the remaining five (BRCA1, TRIM37, RNF25, CDC27, and UBE2H) were up-regulated in tumor tissue compared to normal pancreatic tissue." (PMID 33414811, 2020). "Similar to NCCRP1, USP19 is aberrantly expressed in multiple cancers and may act as a tumour suppressor gene or oncogene, which relies upon the tumour type." (PMID 38106991, 2023). "Our paradoxical results may be due to the fact that NCCRP1 in PC tissues is not expressed mainly in tumour cells, but in stroma cells such as immune cells and fibroblasts." (PMID 38106991, 2023). "However, NCCRP1 was upregulated in tumour tissues and not detected in healthy tissues." (PMID 38303549, 2024).
cancer (4 papers, 2011 to 2023). A tumor composed of atypical neoplastic, often pleomorphic cells that invade other tissues. "The IST database system developed by MediSapiens Ltd was used to obtain the data for NCCRP1 mRNA expression in human normal and cancer-derived tissues." (PMID 22087255, 2011). "One plausible explanation for these observations is that NCCRP1 and FBXO6 are needed to target certain glycoproteins that affect the cell cycle for degradation and that the proliferation of cancer cells is impaired when this function is inhibited." (PMID 22087255, 2011).
infection (4 papers, 2022 to 2025). The state of being infected such as from the introduction of a foreign agent such as serum, vaccine, antigenic substance or organism. "Moreover, recent studies in tilapia and large yellow croaker revealed that NCCRP1 is a cytoplasmic protein that is strongly activated following pathogenic infection." (PMID 41153878, 2025). "Regarding the cell-mediated response related genes, NCCRP-1, TCR-γ, CD4, and CD8 were up-regulated in the sea bass brain with higher levels of NCCRP1 and TCR-γ upon infection with the mutant isolate at 3 dpi, which could be related to the up-regulation of IL-1b." (PMID 35215144, 2022).
bacterial infection (2 papers, 2024 to 2025). "Although previous studies demonstrated the presence of NCCRP1 transcripts in the tilapia brain, with induction evident during bacterial infection, the distribution of NCCs (NCCRP1-positive cells) in the tilapia brain remains unclear." (PMID 39011038, 2024). "Subsequently, the developmental trajectories of NCCs under bacterial infection were fitted, leading to the identification of hundreds of differentiation-related antibacterial genes, including the universal NCC marker NCCRP1." (PMID 41153878, 2025). "Notably, NCCRP1, the highest marker in the fish NCC subpopulation, displayed a significant and sharp increase under bacterial infection." (PMID 39011038, 2024).
NCCRP1 also shares sentences with these, for which no sentence is quoted: breast carcinoma (2 papers); viral infections (1).